LINC01370 (long independently transcribed non-coding RNA 1370)
Synonyms: HI-LNC25; HILNC25
Gene: Long non-coding RNA gene on chromosome 20 (40,004,213 to 40,044,062, forward strand). Ensembl gene ENSG00000237767.
Diseases named in the same sentence as LINC01370 in open-access papers:
LINC01370 is named in the same sentence as 2 diseases in open-access papers, as found by Europe PMC text mining. Sharing a sentence is not in itself a finding about the gene and the disease. The quoted sentences say what the papers report.
tumor (2 papers, 2024). "Finally, among the genes differentially expressed in opposite directions for the male tumor:tumor-adjacent and female tumor:tumor-adjacent comparisons, the majority still had logFCs less than 1.5, with only LINC01370 and PNMA3 demonstrating logFCs greater than 1.5 in females and none in males." (PMID 39005337, 2024). "Here, we confirmed that LINC01370 was abnormally downregulated in HCC tissues with HCC cells, LINC01370 was found to be a tumor inhibitory factor within HCC, and LINC01370 overexpression remarkably repressed HCC cell proliferation, migration, and invasion." (PMID 39090419, 2024). "However, LINC01370 expression did not significantly correlate with tumor TNM stage, disease-free survival, or overall survival in patients with HCC." (PMID 39090419, 2024).
LINC01370 also shares sentences with these, for which no sentence is quoted: diabetes (1 paper).